TMPRSS2 (transmembrane serine protease 2)
Diseases named in the same sentence as TMPRSS2 in open-access papers (continued):
Sharing a sentence is not in itself a finding about the gene and the disease.
infection (continued). "The data demonstrate that infection is restricted to sites containing both ACE2 and TMPRSS2, the latter is expressed in the primary and secondary bronchi whereas ACE2 is predominantly observed in the bronchioles and alveoli." (PMID 35255100, 2022). "To confirm these PFU results, we transfected VeroE6/TMPRSS2 cells with ASO-ORF1b, ASO-N or ASO-C, followed by infection, 5 h later, with a recombinant virus expressing a ZsGreen reporter gene (SARS-CoV-2/ZsGreen)." (PMID 36386681, 2022). "Following the infection process, the RBD domain binds ACE-2 (open conformation); the transmembrane serine protease 2 (TMPRSS2) from the host cell recognizes and cuts the spike into the S1 and S2 subunits." (PMID 36013424, 2022). "Monocytes with cell surface ACE2 and TMPRSS2 were efficiently infected by SARS-CoV-2, and infection was almost completely blocked by the viral replication inhibitor remdesivir, anti-ACE2 antibodies, and the TMPRSS2 inhibitor camostat." (PMID 36085197, 2022). "To confirm whether Omicron variant infection was mainly dependent on endocytosis but not TMPRSS2 pathway, we compared the effect of bafilomycin A1, chloroquine (an endocytosis inhibitor) and camostat (a TMPRSS2 inhibitor) on the replication of Omicron and Delta variants." (PMID 34951565, 2022). "Other host factors, including transmembrane serine protease 2 (TMPRSS2) and neuropillin 1 (NRP1), also have roles in the infection process." (PMID 35277472, 2022). "Moreover, our data also demonstrated that teicoplanin was able to potently inhibit the infection of both live SARS-CoV-2 viruses and different pseudotyped SARS-CoV-2 mutants by inhibiting the enzymatic activity of CTSL and preventing S proteins activation in TMPRSS2-deficient cells." (PMID 35572668, 2022). "During cellular infection by SARS-CoV-2, the trimeric spike (S) proteins located on the viral surface enter the host cell through the ACE2 receptor and TMPRSS2." (PMID 35646741, 2022). "TMPRSS2 is a key protease for the entry of SARS-CoV-2 into cells, and TMPRSS2 is able to cleave the SARS-CoV-2 spike protein to initiate virus invasion and infection of cells." (PMID 36329841, 2022). "Since SARS-CoV-2 requires the co-expression of proteases TMPRSS2 and/or FURIN for infection, we determined their expression in a subset of patients (n = 38), including all ACE2+ patients (n = 21)." (PMID 36077610, 2022). "In HEK293T-ACE2/TMPRSS2 cells, the viral RNA level in CACNA1C-silenced cells was lower than that in siControl-transfected cells at 6 h post-infection." (PMID 35176124, 2022). "We show that LFC and the corresponding synthetic peptide pLF1 designed by us from the N-terminal region of LF inhibit TMPRSS2, and subsequently, SARS-CoV-2 priming and infection of target cells." (PMID 36081512, 2022). "The differences in the infectivity of the WT and BriSΔ viruses were then compared on Vero E6, Vero E6/TMPRSS2, Caco-2, Caco-2-ACE2 and Calu-3 cells using a range of virus dilutions for infection." (PMID 35017512, 2022). "For successful infection at lower MOIs of 0.001, the combined expression of ACE2 and TMPRSS2 was required." (PMID 35013790, 2022). "Since our data suggested that SARS-CoV-2 uses only one entry mechanism in both Vero E6 and Vero E6/TMPRSS2 cells, the evaluation of the VOC entry mechanism was performed only on the in vitro model that most resembled the physiological target of the infection." (PMID 35746703, 2022). "Being able to detect ACE2, TMPRSS2, and infected cells in a 3D format, we focused on examining overlapping regions of ACE2 and SARS-CoV-2 infection to assess if an infection is restricted to specific regions." (PMID 35255100, 2022). "Subsequently, the S protein gets cleaved by the transmembrane protease serine 2 (TMPRSS2), the SARS-CoV-2 co-receptor, to establish the infection." (PMID 35284964, 2022). "Infection occurs in cells that express ACE2 (angiotensin-converting enzyme 2) and TMPRSS2 (transmembrane serine protease 2)." (PMID 36140114, 2022).
infection (continued). "The cellular serine protease TMPRSS2 primes SARS-CoV-2 spike protein and facilitates viral entry through the plasma membrane route during infection." (PMID 36228039, 2022). "While only the TMPRSS2 protease cleavage occurs on the cell surface, the HR2 peptide inhibits infection in VeroE6 cells possessing only the cathepsin pathway." (PMID 36122200, 2022). "Additionally, hesperetin and hesperidin suppressed the infection of VeroE6 cells using lentiviral-based pseudo-particles with wild types and variants of spike proteins, by blocking the interaction between the spike protein and cellular receptor ACE2 and reducing ACE2, and TMPRSS2 expression." (PMID 36142258, 2022). "To examine the mechanism by which JGF prevented infection with SARS-CoV-2, we focused on the effects of the JGF-regulated expressions of ACE2 and TMPRSS2." (PMID 35387343, 2022). "It is well known that the TMPRSS2 (a serine protease) interacts with the spike protein of the SARS-CoV-2 virus and primes it for infection in host cells." (PMID 35296517, 2022). "The SARS-CoV-2 spike protein, transmembrane protease serine 2 (TMPRSS2) and human receptor angiotensin-converting enzyme 2 (ACE2) are the major host-pathogen determinants affecting infection." (PMID 36329841, 2022). "The SARS-CoV-2 S protein, transmembrane protease serine 2 (TMPRSS2), and human receptor ACE2 are the main determinants of host pathogens affecting infection." (PMID 36817101, 2022). "To further examine our PV entry and infection findings, we studied the expression of ACE2 and TMPRSS2 across our target cells using qPCR analysis of RNA extracts from cell lysates." (PMID 35104837, 2022). "The squamous cells of the tongue and periodontal tissues express angiotensin-converting enzyme-2 (ACE-2), a SARS-CoV-2 receptor, transmembrane protease serine 2 (TMPRSS2), and furin, which are proteases that promote infection, and saliva can harbor SARS-CoV-2." (PMID 34813596, 2021). "Indeed, although there is no demonstrated association between TMPRSS2 and kinase inhibition, it has been postulated that kinase inhibition could result in the inhibition of TMPRSS2 function, localization, or activity, and the observed blocking of the infection." (PMID 33467029, 2021). "TMPRSS2-mediated cleavage of the S protein is essential for SARS-CoV-2 entry, and exosome-mediated transfer of ACE2 increases SARS-CoV-2 entry and infection." (PMID 34394121, 2021). "We identified TMPRSS2 and TMPRSS11D as host TTSPs that mediate trypsin-independent and multicycle infection by human and animal RVA strains." (PMID 33762412, 2021). "SARS-CoV-2 primarily targets the respiratory tract and infection is mediated by spike (S) protein binding to the human angiotensin-converting enzyme 2 (ACE2), where the transmembrane protease serine 2 (TMPRSS2) triggers fusion of the viral and cell membranes." (PMID 33852916, 2021). "Expression of ACE2, TMPRSS2, and Cathepsin B in organotypic cultures was consistent with the in vivo distribution of SARS-CoV-2 during the first 4 days of infection." (PMID 34608167, 2021). "Along with ACE-2, also TMPRSS2 is used by SARS-CoV-2 as spike protein priming, and its block is proved to be efficient in stopping the infection." (PMID 34769246, 2021). "TMPRSS2 and TMPRSS4 have been demonstrated to be important for cleavage of SARS-CoV-2 to allow entry and infection of host cells." (PMID 34051791, 2021). "To show the utility of periscope for the investigation of important biological questions, we applied it to sequencing data from an in vitro infection time course using VeroE6 cells that were either WT, overexpressing ACE2, or overexpressing ACE2 and TMPRSS2." (PMID 33722935, 2021). "TMPRSS2 is expressed in the respiratory epithelium, and it is a well-studied member of the TTSP family with respect to the role of TTSPs in infection by respiratory viruses (13, –, 15)." (PMID 33762412, 2021).
infection (continued). "In conjunction with the androgen receptor, androgens activate TMPRSS2 expression, which plays a vital role in internalizing the SARS-CO-V2 virus and productive infection." (PMID 33915795, 2021). "Transmembrane serine protease 2 (TMPRSS2), a protease that cleaves the SARS-CoV-2 spike protein to facilitate infection and is necessary for viral binding to ACE2, membrane fusion, and cell entry, is also not present on Hofbauer cells." (PMID 33920814, 2021). "Infection is mediated by the spike protein binding human angiotensin-converting enzyme (ACE2); cleavage of spike by the transmembrane protease serine 2 (TMPRSS2) triggers fusion of the viral and cell membranes." (PMID 34545347, 2021). "In this study, we demonstrated that the host proteases TMPRSS2 and TMPRSS11D mediate the trypsin-independent infection and growth of RVAs." (PMID 33762412, 2021). "SARS-CoV-2 infection of the gastrointestinal system affects gut inflammation both directly and indirectly following infection of intestinal epithelial cells through the ACE2 and transmembrane protease serine 2 (TMPRSS2) viral entry system." (PMID 34291074, 2021). "For example, TMPRSS2 and TMPRSS4 mRNAs were more abundant in Caco-2 cells than A549 cells, but the infection was more pronounced in A549." (PMID 34064066, 2021). "Similar findings were observed for TMPRSS2-facilitated, ACE2-dependent infection, indicating that when ACE2 is expressed on the plasma membrane at high concentrations these host proteins that assist SARS-CoV-2 entry are no longer required." (PMID 34797899, 2021). "The infection by SARS-CoV-2 was mainly mediated by Furin and TMPRSS2, while PCoV-GD and PCoV-GX mainly depend on Cathepsin L. Extensive cross-neutralization was found between SARS-CoV-2 and PCoV-GD." (PMID 33824288, 2021). "First, TMPRSS2 and TMPRSS11D expression facilitated trypsin-independent infection and progeny virus production." (PMID 33762412, 2021). "For example, when titers are adjusted so that infections by SARS1- and SARS2-PV are identical in the presence of TMPRSS2, their efficiencies are markedly different in its absence." (PMID 33465165, 2021). "First we confirm expression of the receptor ACE2 and the serine protease TMPRSS2 in human primary airway epithelial tissues cultured in the PREDICT96-ALI system, a key attribute toward modeling infection with HCoV-NL63 and SARS-CoV-2." (PMID 34294757, 2021). "Based on the structure of MSPL, we also constructed a homology model of TMPRSS2, which is essential for the activation of the SARS-CoV-2 spike protein and infection." (PMID 33820827, 2021). "The infection can propagate further as ACE2 and TMPRSS2 expression is found throughout the airway epithelium, particularly in ciliated and secretory cells." (PMID 34026781, 2021). "Abundant expression of ACE2, TMPRSS2, and FURIN was observed on the apical side of ciliated cells, which support massive replication of SARS-CoV2 during early stage of infection." (PMID 34760721, 2021). "First, as hMDM were resistant to infection by SARS-CoV-2, we assessed the expression levels of the viral cell receptor ACE2, as well as TMPRSS2, a serine protease involved in the proteolytic activation of the spike protein." (PMID 33912475, 2021). "Fourth, cells expressing TMPRSS2 and TMPRSS11D permitted the infectious entry of immature RVA virions, and this infection was inhibited by treatment with a protease inhibitor." (PMID 33762412, 2021). "The infection of SARS-CoV-2 requires cleavage at the S1/S2 site by furin, followed by cleavage at the S2′ site by TMPRSS2." (PMID 33820827, 2021). "Pre-processing and subsequent proteolytic digestion of the S protein, respectively by host proprotein convertase furin and host transmembrane protease serine 2 (TMPRSS2), are also required for establishing successful infection." (PMID 34201797, 2021).
infection (continued). "Based on the observations in this study, we propose a model in which TMPRSS2 and TMPRSS11D mediate proteolytic activation at the viral entry step and facilitate trypsin-independent infection by RVAs in MA104 cells." (PMID 33762412, 2021). "Both tetraspanin CD9 and TMPRSS2 facilitate MERS coronavirus entry and a robust infection of mouse lungs in vivo." (PMID 34394121, 2021). "Next, we electroporated a single dilution of each serum into Vero ACE2/TMPRSS2 cells, challenged them with SARS‐CoV‐2 and quantified infection by RT–qPCR." (PMID 34323299, 2021). "The best characterized and most extensively studied surrogate lung cell infection model for SARS-CoV-2 are Calu-3 cells expressing ACE2 and TMPRSS2 endogenously." (PMID 33918670, 2021). "We therefore tested a protease inhibitor drug, nafamostat, which can inhibit TMPRSS2, in the Intestine Chip NL63 infection model." (PMID 34759819, 2021). "Nasal cells are the site of the first step of infection; these cells express the highest levels of angiotensin-converting enzyme 2 (ACE2) and of the cellular serine protease TMPRSS2, the main entry receptors for SARS-CoV-2." (PMID 34573877, 2021). "Other broadly expressed host proteins contribute to an effective infection of SARS-CoV-2 into human cells including the proteases furin and furin-like proteins, transmembrane protease serine 2 (TMPRSS2), and the cathepsin B and L (CatB/L)." (PMID 33036180, 2020). "While TMPRSS2, ADAM17, and furin are co-receptors needed to complete the infection process, ACE2 serves as the receptor for SARS-CoV-2’s spike protein, enabling the virus to enter the host cell upon interaction with the S protein." (PMID 33271762, 2020). "The co-expression of both ACE2 and TMPRSS2 genes is necessary for infection to occur, since SARS-CoV-2 uses the ACE2 receptor for entry and the serine protease TMPRSS2 for S protein priming." (PMID 33246480, 2020). "For initial infection, ACE2-expressing cells, with the co-expression of TMPRSS2 and Furin as a plus, in the respiratory tract are the primary targets." (PMID 33134888, 2020). "To determine the function of TMPRSS serine proteases in facilitating SARS-CoV-2 S mediated infection of primary human IECs, we used CRISPR/Cas9 gene editing to deplete TMPRSS2 or TMPRSS4 expression in human duodenum enteroids." (PMID 32404436, 2020). "Arguably, the most important advantage of the acquired furin site is in redirecting TMPRSS2 function for proteolytic cleavage of SARS-CoV-2, opening a possibility of cell-to-cell propagation of infection in seemingly asymptomatic patients." (PMID 33142989, 2020). "The host cell proteases, like transmembrane protease serine 2 (TMPRSS2), help in SARS-CoV-2 entry and infection." (PMID 33228225, 2020). "Both SARS-CoV-2 and SARS-CoV bind to human ACE2 90 and use transmembrane protease serine 2 (TMPRSS2) to complete cell entry and infection 89,91." (PMID 33061805, 2020). "Here, Calu-3 cells were treated once with T-ex5 PPMO for 24 h before infection with SARS-CoV-2 to inhibit the production of normal TMPRSS2-mRNA and deplete enzymatically active TMPRSS2 present in the cells." (PMID 32703818, 2020). "Infection of the H7N9 influenza and H1N1 influenza A subtype viruses are also mediated by TMPRSS2-cleaved ACE2." (PMID 32604730, 2020). "Blocking TMPRSS2 protease activity blocks ACE2-mediated entry of SARS-CoV-2, suggesting that co-expression of both genes is required for infection." (PMID 32750256, 2020). "A clinically established and commercially available, serine protease inhibitor, camostat mesylate, has partially inhibited the infection by HCoV-NL63 and SARS-CoV in HeLa cell lines, which express TMPRSS2 and ACE2." (PMID 33664752, 2020). "However, TMPRSS2 protein seemed to be expressed at relatively low level in the spermatids of the testis as well as stromal cells of ovary and adrenal gland, suggesting different probabilities for them to establish efficient infection by SARS-CoV-2 virus during viremia." (PMID 33134888, 2020).
infection (continued). "The same study confirms an even greater enhancement of SARS-CoV-2 in bypassing IFITM3 defense via TMPRSS2 activation of plasma membrane fusion, and reports compatibility with HCoV-OC43 mode of enhanced infection." (PMID 33240681, 2020). "Analysis of the connection between SARS-CoV-2 interactome revealed direct interaction of the virus glycoprotein S with 3 of the 11 virus-infection related proteins identified as incomplete in the ACE2 network (ACE2, CLEC4M, and TMPRSS2)." (PMID 33233425, 2020). "SARS-CoV-2 initiate its infection via the interaction with angiotensin-converting enzyme 2 (ACE2) receptors and transmembrane protease, serine 2 (TMPRSS2) on host cell membrane." (PMID 33178026, 2020). "In this study, the syncytium formation (cell-cell fusion) was observed clearly in Vero/TMPRSS2, Vero/MSPL cell lines stably expressing TMPRSS2 and MSPL post-infection, which most likely promote the enhancement of PEDV infection." (PMID 32471322, 2020). "Importantly, due to the structural similarity between MERS-CoV / SARS-CoV and SARS-CoV-2, we hypothesize that the described mRNA/miRNA interactions may contribute to maintenance of ACE2 / TMPRSS2 expression levels during coronavirus infection, thus regulating the infection process." (PMID 32726325, 2020). "The SARS-CoV-2 virus responsible for the infection depends on two human genes: the human receptor angiotensin converting enzyme 2 (ACE2) for cell invasion, and the serine protease TMPRSS2 for S protein priming." (PMID 32582302, 2020). "Our data demonstrate that EVs containing ACE2, alone or in combination with TMPRSS2, block SARS‐CoV‐2 Spike‐dependent infection in a much more efficient manner than soluble ACE2." (PMID 33391636, 2020). "In the same way, with Vero cells, which hardly express TMPRSS2, camostat mesylate had little effect in reducing SARS-CoV-2 infection, whereas E-64d, which blocked Cathepsin B/L reduced nearly 100% of the infections." (PMID 33290397, 2020). "However, we caution that a cell may not need to be TMPRSS2+ to be susceptible to infection, since it has been demonstrated the TMPRSS2 protein is secreted from nasal airway epithelial cells." (PMID 33046696, 2020). "Infection significantly increased the expression of ACE2, TMPRSS2, ADAM17, TGFB1, CTGF, VEGFA and FN1 but resulted in trends towards decreases in TIMP3 (p = 0.083) and AGF (p = 0.086) in A549 cells compared to control cells." (PMID 32664949, 2020). "As soon as the cathepsin-L-dependent endocytic pathway of infection (via ACE2 receptor) is participating, the effectiveness of TMPRSS2 inhibitors decreases rapidly." (PMID 32668803, 2020). "Blocking of TMPRSS2 may not be associated with severe unwanted side effects, since Tmprss2−/− mice are healthy and do not show any phenotypic alterations in the absence of an infection." (PMID 24348248, 2013). "Only very mild pathogenesis was observed in Tmprss2 mutant mice after infection with H1N1 virus and less severe pathogenesis was observed after infection with H3N2 virus." (PMID 24348248, 2013). "Furthermore, MH-1 decreased the infection of SARS-CoV-2 in T lymphocytes that highly express HLA-C but have low levels of ACE2 and TMPRSS2." (PMID 41699454, 2026). "Furthermore, the membrane-bound serine proteases TMPRSS2 and TMPRSS11D also facilitated infection and syncytia formation in a strain-dependent manner." (PMID 41505483, 2026). "Other factors, such as the transmembrane protease serine 2 (TMPRSS2) which is most abundantly expressed in multiciliated cells of human airway tissues, may also contribute to the infection of these cells in consort with DPP4." (PMID 40048293, 2025). "In TMPRSS2-expressing cells, E-64d failed to inhibit infection, whereas camostat mesylate significantly reduced the enhanced infection observed in ΔDAZAP2 cells." (PMID 40833112, 2025).